AGER (advanced glycosylation end-product specific receptor)
Description:
Cell surface pattern recognition receptor that senses endogenous stress signals with a broad ligand repertoire including advanced glycation end products, S100 proteins, high-mobility group box 1 protein/HMGB1, amyloid beta/APP oligomers, nucleic acids, histones, phospholipids and glycosaminoglycans. Advanced glycation end products (AGEs) are nonenzymatically glycosylated proteins which accumulate in vascular tissue in aging and at an accelerated rate in diabetes. These ligands accumulate at inflammatory sites during the pathogenesis of various diseases including diabetes, vascular complications, neurodegenerative disorders and cancers, and RAGE transduces their binding into pro-inflammatory responses. Upon ligand binding, uses TIRAP and MYD88 as adapters to transduce the signal ultimately leading to the induction of inflammatory cytokines IL6, IL8 and TNFalpha through activation of NF-kappa-B. Interaction with S100A12 on endothelium, mononuclear phagocytes, and lymphocytes triggers cellular activation, with generation of key pro-inflammatory mediators. Contributes to the translocation of amyloid-beta peptide (ABPP) across the cell membrane from the extracellular to the intracellular space in cortical neurons. ABPP-initiated RAGE signaling, especially stimulation of p38 mitogen-activated protein kinase (MAPK), has the capacity to drive a transport system delivering ABPP as a complex with RAGE to the intraneuronal space. Participates in endothelial albumin transcytosis together with HMGB1 through the RAGE/SRC/Caveolin-1 pathway, leading to endothelial hyperpermeability. Mediates the loading of HMGB1 in extracellular vesicles (EVs) that shuttle HMGB1 to hepatocytes by transferrin-mediated endocytosis and subsequently promote hepatocyte pyroptosis by activating the NLRP3 inflammasome. Binds to DNA and promotes extracellular hypomethylated DNA (CpG DNA) uptake by cells via the endosomal route to activate inflammatory responses. Mediates phagocytosis by non-professional phagocytes (NPP) and this is enhanced by binding to ligands including RNA, DNA, HMGB1 and histones. Promotes NPP-mediated phagocytosis of Saccharomyces cerevisiae spores by binding to RNA attached to the spore wall. Also promotes NPP-mediated phagocytosis of apoptotic cells. Following DNA damage, recruited to DNA double-strand break sites where it colocalizes with the MRN repair complex via interaction with double-strand break repair protein MRE11 (By similarity). Enhances the endonuclease activity of MRE11, promoting the end resection of damaged DNA (By similarity). Promotes DNA damage repair in trophoblasts which enhances trophoblast invasion and contributes to placental development and maintenance. Protects cells from DNA replication stress by localizing to damaged replication forks where it stabilizes the MCM2-7 complex and promotes faithful progression of the replication fork. Mediates the production of reactive oxygen species (ROS) in human endothelial cells.
Synonyms: RAGE; SCARJ1; sRAGE
Tractability: Small molecule: a drug acting on it is in phase 2 or 3 trials; a structure with a bound ligand is known; a high-quality ligand is known; it has a high-quality binding pocket. Antibody: UniProt places it where antibodies can reach, with high confidence; its Gene Ontology location is reachable by antibodies, with high confidence; UniProt predicts a signal peptide or a membrane-spanning region. PROTAC: UniProt records ubiquitination sites on it; a small molecule that binds it is known.
Target class: Membrane receptor
Gene: Protein-coding gene on chromosome 6 (32,180,963 to 32,184,344, reverse strand). Ensembl gene ENSG00000204305.
Subcellular location: Cell membrane; Cell projection, phagocytic cup; Early endosome; Nucleus; Cell membrane (Isoform 1); Secreted (Isoform 2); Cell membrane (Isoform 10)
Subcellular location (Human Protein Atlas): Cell Junctions; Plasma membrane; Nucleoli fibrillar center; Predicted to be secreted
Pathways (Reactome):
Immune System: Advanced glycosylation endproduct receptor signaling; TAK1-dependent IKK and NF-kappa-B activation; TRAF6 mediated NF-kB activation
Gene Ontology:
Molecular function: amyloid-beta binding; DNA binding; histone binding; identical protein binding; molecular adaptor activity; protein binding; protein-containing complex binding; RNA binding; S100 protein binding; signaling receptor activity; advanced glycation end-product receptor activity; scavenger receptor activity; transmembrane signaling receptor activity
Biological process: astrocyte activation; glucose mediated signaling pathway; intracellular signal transduction; learning or memory; microglial cell activation; negative regulation of interleukin-10 production; negative regulation of long-term synaptic depression; negative regulation of long-term synaptic potentiation; neuron projection development; phagocytosis; positive regulation of activated T cell proliferation; positive regulation of amyloid precursor protein catabolic process; positive regulation of dendritic cell differentiation; positive regulation of DNA-templated DNA replication; positive regulation of ERK1 and ERK2 cascade; positive regulation of heterotypic cell-cell adhesion; positive regulation of interleukin-12 production; positive regulation of JNK cascade; positive regulation of monocyte extravasation; positive regulation of non-canonical NF-kappaB signal transduction; positive regulation of p38MAPK cascade; regulation of CD4-positive, alpha-beta T cell activation; regulation of spontaneous synaptic transmission; regulation of T cell mediated cytotoxicity; transport across blood-brain barrier; and 29 more
Cellular component: apical plasma membrane; cell junction; cell surface; early endosome; nucleus; phagocytic cup; plasma membrane; postsynapse; extracellular region
Genetic constraint (gnomAD): Loss-of-function variants: 48 observed, 57.19 expected, observed/expected ratio (o/e) 0.84, 90% interval 0.67 to 1.07. The upper end of that interval is the gene's LOEUF score, 1.07, which puts it in group 4 of 6, group 1 being the genes least tolerant of losing a copy. Missense variants: 489 observed, 541.8 expected, observed/expected ratio (o/e) 0.9, 90% interval 0.84 to 0.97. Synonymous variants: 170 observed, 210.33 expected, observed/expected ratio (o/e) 0.81, 90% interval 0.71 to 0.92.
Homologues: Orthologues: chimpanzee AGER (99% identical), macaque AGER (96% identical), pig AGER (84% identical), rabbit AGER (83% identical), mouse Ager (78% identical), guinea pig AGER (73% identical), rat Ager (73% identical), dog AGER (71% identical), zebrafish si:ch211-79k12.1 (9% identical). Paralogues in human: MCAM (24% identical), ALCAM (23% identical), BCAM (22% identical).
Diseases named in the same sentence as AGER in open-access papers:
AGER is named in the same sentence as 201 diseases in open-access papers, as found by Europe PMC text mining. Sharing a sentence is not in itself a finding about the gene and the disease. The quoted sentences say what the papers report.
diabetes (80 papers, 2007 to 2026). "This evidence strengthens the link between AGER signaling and complement activation in the context of hyperglycemia, emphasizing their potential role in diabetes-associated complications." (PMID 38791494, 2024). "Several single nucleotide polymorphisms (SNPs) in the AGER gene have been reported to be associated with diabetes or its complications." (PMID 35330392, 2022). "Multiple single nucleotide polymorphisms (SNPs) of AGER gene have been reported for association with diabetes and chronic diabetic complications." (PMID 34512554, 2021). "BHLHE41 also has a role in immune function and in addition toCAMK1D,AGER is implicated in diabetes along with the narcolepsy-related gene,HLA-DQB1." (PMID 34745571, 2020). "Extending beyond overall comparisons, we noticed that risk effects of AGER genetic variants on CAD were strikingly potentiated in patients with diabetes mellitus or renal disease." (PMID 23894685, 2013). "Our findings demonstrated that association of AGER genetic polymorphisms with CAD was potentiated in patients with diabetes mellitus or renal disease." (PMID 23894685, 2013). "Taken together, our findings collectively demonstrated that association of AGER genetic polymorphisms with CAD was potentiated in patients with diabetes mellitus or renal disease." (PMID 23894685, 2013). "Moreover, various polymorphisms in the AGER gene have been linked to diabetes, its complications, and plasma sRAGE levels." (PMID 37240472, 2023). "However, in people with diabetes, due to increased production and mutation in the AGER gene, there is an accumulation of AGEs." (PMID 35099614, 2022). "However, the evidence showing detrimental effects of AGER polymorphism on bone metabolism remains to be elucidated in cases of diabetes." (PMID 34512554, 2021). "Accumulation of soluble forms of the receptor for advanced glycation end products (RAGEs, also known as AGER) in serum/plasma has been implicated in multiple physiological and pathological processes, including aging, diabetes, neurodegeneration, ischemia/reperfusion injury, among others." (PMID 31899686, 2020). "Soluble RAGE levels were found to be significantly associated with CAD and diabetes in many studies, and the association between haplotypes in the AGER gene and diabetic ischemic heart disease in the current study indicated that sRAGE levels could serve as a marker of diabetic ischemic disease." (PMID 35330392, 2022). "Moreover, a higher cellular AGER expression was illustrated only in the cells from the group of diabetics with impaired osteogenic differentiation, and that higher AGER expression was shown to be associated with the differentiation potential toward osteoblasts." (PMID 34512554, 2021). "A highly polymorphic gene, variants in AGER, which is responsible for encoding the RAGE protein, has been implicated in multiple diseases such as cancer, diabetes complications, COPD, acute respiratory distress syndrome, and cardiovascular disease." (PMID 40225935, 2024). "While AGER expression is low in most cell types in healthy conditions, it is upregulated in several disease states, including diabetes." (PMID 37988162, 2024). "In animal models of diabetes, mice overexpressing AGER display increased glomerular hypertrophy, albuminuria, serum creatinine, and advanced glomerulosclerosis, whereas AGER knockout mice are protected from these pathogenic features." (PMID 37240472, 2023). "AGER expression is upregulated in many diseases like Alzheimer’s disease, diabetes mellitus, atherosclerosis, and rheumatoid arthritis." (PMID 35099614, 2022). "The multivariate analysis demonstrated that both age and AGER expression correlated with the potential for osteogenic differentiation in the PBMC isolated from patients with diabetes." (PMID 34512554, 2021). "This suggests that rs1800264 is involved in AGER gene regulation and influences the pathogenesis of inflammatory diseases or diabetes-related vascular complications." (PMID 30863465, 2019).
diabetes (continued). "It is expected that poorly controlled diabetes patients have high circulating levels of AGEs for prolonged periods throughout their lifetime, which induces a more striking increase in AGER expression than found in our experiment." (PMID 27582133, 2016). "Moreover, we observed the elevated levels of MNCV in T1D mice with global deletion of Diaph1 and AGER genes vs. WT mice at six months of diabetes (p ≤ 0.0001)." (PMID 41303665, 2025). "Research shows that, there are significantly more macrophages in diabetes plaques, and the expression of AGER is increased in monocytes/macrophages, the key cells in atherosclerosis, so diabetes plaques show more expression of AGER." (PMID 39296548, 2024). "The interaction between AGEs and AGER promotes the occurrence of inflammation and OS, leading to the formation of foam cells in macrophages, which leads to the occurrence and development of diabetes related atherosclerosis." (PMID 39296548, 2024). "With an aging CF population and diabetes being the most prevalent comorbidity, the AGER gene may be of clinical importance in the future." (PMID 40225935, 2024). "At the same time, diabetes plaques show more expression of AGER (especially in Macrophages)." (PMID 39296548, 2024). "A meta-analysis including 27 original articles showed that AGER genetic polymorphisms with CAD were potentiated in patients with diabetes mellitus disease, but the association was not consistently significant." (PMID 35330392, 2022). "Vitamin D might contribute in ameliorating diabetes complications not only by improving blood glucose and insulin levels, but also by suppressing AGER and OGT gene expression in the liver." (PMID 31231498, 2019). "However, only a few studies investigate the role of miRNAs in regulating AGE/AGER signaling related to diabetic manifestations and during diabetes." (PMID 29752466, 2018). "The authors had hypothesized that diabetes and/or renal disease might precipitate the occurrence of coronary artery disease via the inheritance of genetic defects leading to the transcriptional activation of AGER, thus being correlated with patient ethnicity." (PMID 30863465, 2019). "It has therefore been hypothesized that diabetes mellitus and/or renal disease might favor the occurrence of coronary artery disease through the inheritance of genetic defects leading to the transcriptional activation of AGER." (PMID 30863465, 2019). "AGER, also is shown as one of the main responsible factors in tumorigenesis of HCC cells in the presence of high glucose for diabetes." (PMID 35331184, 2022). "In the skin of human subjects with diabetes, RAGE expression was upregulated, particularly in the dermal and subcutaneous vascular endothelium, and the extent of AGER mRNA transcript elevation in the diabetic skin was higher in severe vs. milder or no neuropathy." (PMID 35562970, 2022). "Due to the increased expression of AGER in these cells in people with diabetes compared to non-diabetics, muller cells are hypothesized to act as a regulator of diabetic retinopathy." (PMID 35099614, 2022). "On the basis of previous work and the findings of this study, it is reasonable to hypothesize that diabetes mellitus and/or renal disease might precipitate the occurrence of CAD via the inheritance of genetic defects leading to the transcriptional activation of AGER." (PMID 23894685, 2013). "However, this association did not remain statistically significant after adjusting for diabetes duration, HbA1c, diastolic BP and the presence of other DKD-associated polymorphisms located in three different genes, namely AGER-429T/C and 2184A/G, LTA 252A/G, and NOS3 774C/T and E298D." (PMID 26594247, 2015).
Hyperglycemia (25 papers, 2011 to 2025). An increased concentration of glucose in the blood. "Under normoglycemic conditions, the A-allele of the −374 T/A polymorphism increased the AGER transcription in vitro, while in hyperglycemia, the T-allele of the −374 T/A polymorphism appeared to behave similarly." (PMID 37110179, 2023). "We found that hyperglycemia reduces both the axon and the g ratio in WT mice, but deleting Diaph1 and AGER together prevents this reduction to a similar extent." (PMID 41303665, 2025). "Intracellular hyperglycemia can increase production of advanced glycation end products (AGEs), promoting the interaction of AGEs and the advanced glycosylation end product-specific receptor (AGER, also known as RAGE)." (PMID 38645427, 2024). "In response to hyperglycemia, AGER is activated by S100A8/A9 on hepatic Kupffer cells, leading to the secretion of IL-6." (PMID 35330392, 2022). "Long-standing hyperglycaemia results in the formation and accumulation of advanced glycation end products (AGEs), which can activate the receptor for AGE (RAGE; also known as AGER) and cause neuronal damage." (PMID 29930087, 2018). "This study demonstrated that the expression of AGER in T2DM was lower than that in the control group, which may be associated with the decrease of AGER expression due to the excessive accumulation of AGEs caused by long-term hyperglycemia." (PMID 39296548, 2024). "Put together, our data indicates that DRKO mice were almost completely devoid of negative signs of hyperglycemia, hence we examined the effect of Diaph1 and AGER deletion on the functionality of the sciatic nerve fibers." (PMID 41303665, 2025).
Obesity (25 papers, 2011 to 2026). Accumulation of substantial excess body fat. "PCSK9, MST1, and RPS6K1 predominantly mediated the detrimental effect of sedentary behavior on CAD, while the effect of smoking was mainly mediated by RGMB, PCSK9, ITPKA, RPS6KA1, and AGER, which partially aligned with the observed association pattern between obesity and CAD." (PMID 38049831, 2023). "A recent study identified six proteins (LEPR, IGFBP1, WFIKKN2, AGER, DPT, and CTSA), including WFIKKN2, which may have a causal role in the development of obesity." (PMID 39273278, 2024). "As shown in this study, IBC patients with obesity and highly proliferative tumors had increased percentages of TLR4 and AGER." (PMID 40647480, 2025). "The detrimental effect of obesity on CAD appears to be primarily mediated by MAP1LC3A, ANGPTL4, RPS6KA1, PCSK9, ITPKA, and AGER." (PMID 38049831, 2023). "The percentage of AGER expression (mean 133.8 ± 33.0) was significantly increased (p = 0.05) in IBC patients with subjects with obesity compared to non-IBC individuals with no obesity (mean 86.6 ± 40.9)." (PMID 40647480, 2025). "AGER and MST1 exhibited the highest frequency among the mediating networks, offering potential targets for CAD prevent and treatment, especially in individuals with obesity and unhealthy lifestyle factors." (PMID 38049831, 2023). "Notably, AGER and MST1 exhibited high frequency among the identified mediating networks, which may underscore potential involvements in the pathogenesis and offer promising therapeutic targets to mitigate CAD risk in individuals with obesity and unhealthy lifestyle factors." (PMID 38049831, 2023). "Thus, we conclude that with the exception of the gene encoding PGC1α, genes in the AGE/AGER/DIAPH1 axis, inflammatory and adipocyte metabolism markers are not differentially regulated by the degree of obesity among obese subjects." (PMID 34103691, 2021). "Additionally, a direct correlation between BMI and gene expression was observed for AGER, ANGPT2, CD68, IFI30, NOTCH3 and SPP1, whereas an inverse correlation was achieved for DLL4, PLIN, PNPLA2 and VEGF (genes that were down-regulated due to obesity)." (PMID 33022994, 2020).